INS (insulin)
Diseases named in the same sentence as INS in open-access papers (continued):
Sharing a sentence is not in itself a finding about the gene and the disease.
Insulin resistance (continued). "Furthermore, insulin resistance occurs as a result of placental hormones that antagonize insulin, estrogen, progesterone, human placental lactogen (HPL), human placental growth hormone, cortisol, prolactin, and tumor necrosis factor-alpha (TNF-α)." (PMID 22518122, 2012). "On the other end, raised levels of PED/PEA-15 in insulin-sensitive tissues may lead to insulin resistance, which often accompanies the use of such drugs." (PMID 21618539, 2012). "There is growing evidence supporting the notion that a crosstalk between mitochondria and the insulin signaling cascade could be involved in the etiology of T2D and insulin resistance." (PMID 23236286, 2012). "The difference between line 305 mice and the TG mice in the present study is that the former exhibited insufficient β cell compensation against hepatic insulin resistance, by contrast, the latter showed significantly impaired insulin secretion and decreased β cell mass." (PMID 22384192, 2012). "In addition, a direct effect of leptin has been shown in clinical studies where induced hyperleptinemia contributes to increase insulin resistance, whereas interruption of treatment ameliorates the sensitivity to insulin." (PMID 23056516, 2012). "However, fasting blood glucose and insulin levels, and insulin resistance, were all similar for both OP and OR rats after consuming the moderate fat diet for 4 wk." (PMID 23098187, 2012). "A decreased NO bioavailability may also have a significant impact on the development of insulin resistance; NO modulates insulin-mediated glucose disposal as well as vessels reactivity in insulin-sensitive tissue such as the skeletal muscle." (PMID 22558392, 2012). "The main mechanism through which NAFLD is induced is insulin resistance; a metabolic state in which normal insulin serum concentrations induce an inadequate response, or to attain normal blood glucose levels, we need higher than normal insulin concentrations." (PMID 23346150, 2012). "Furthermore, IL-10 overexpression in mice is able to prevent diet-induced insulin resistance, and indeed we see increased IL-10 expression in the ad-12/15-LO mice fed a high-fat diet with concomitant improvements in insulin sensitivity." (PMID 23326022, 2012). "When insulin secretion can compensate for insulin resistance, normoglycemia can be maintained." (PMID 22550941, 2012). "Thus, despite insulin resistance in adipose tissue, B1−/− mice exhibited improved whole body insulin sensitivity and decreased serum insulin levels in comparison with WT mice." (PMID 23024762, 2012). "Given the close link between insulin resistance and inflammation in adipose tissue, one might expect, based on these data, that B1−/− mice would exhibit local insulin sensitivity, whereas we have observed the opposite phenotype." (PMID 23024762, 2012). "Insulin resistance is thought to arise from impaired insulin signaling in target tissues." (PMID 22110480, 2012). "In addition, we assessed glucose and insulin levels as well as the homeostasis model assessment for insulin resistance (HOMA-IR)." (PMID 22989045, 2012). "However, East Asians have lower insulin secretory capacity to compensate for insulin resistance and therefore easily develop type 2 diabetes." (PMID 23270397, 2012). "Surrogate parameters for insulin resistance and insulin sensitivity." (PMID 22363740, 2012). "In addition, it is widely accepted patients with IGT represented more advanced glycemic disorders compared to those NGT patients with insulin resistance but compensatory insulin production." (PMID 22397368, 2012). "Increasing evidence suggests that abdominal obesity and concomitant development of inflammation are major components of insulin resistance, and elevated levels of pro-inflammatory cytokines secreted from expanded adipose tissue can negatively modulate insulin signaling pathways." (PMID 22463706, 2012).
Insulin resistance (continued). "Abnormalities in other hormones such as reduced secretion of the incretin glucagon-like peptide 1 (GLP-1), hyperglucagonaemia, and raised concentrations of other counter-regulatory hormones also contribute to insulin resistance, reduced insulin secretion, and hyperglycaemia in type 2 diabetes." (PMID 23316348, 2012). "In pre-T2D patients, normoglycemia could be maintained as long as insulin resistance is adequately compensated by increased insulin secretion." (PMID 23024780, 2012). "Recently, several clinical and experimental studies have supported the hypothesis that HCV may induce insulin resistance by interfering with insulin signaling." (PMID 22675572, 2012). "On the other hand, when given chronically at low and high doses in the presence of DEXA-induced insulin resistance, leucine supplementation promotes a clear diabetic state, and the diminishment of insulin levels observed with high doses would indicate a beta cell failure function." (PMID 23363994, 2012). "First, they found that although primary aldosteronism patients (with adrenal adenoma or bilateral adrenal hyperplasia) were more insulin resistant than age-, sex- and BMI–matched normal controls, the severity of the insulin resistance was less evident than in patients with EH." (PMID 22804097, 2012). "Our data on insulin resistance and normal mitochondrial function support the idea that lipids themselves or metabolites of lipid metabolism attribute to impaired response to insulin, e.g. via altered cell membrane properties or by affecting IRS phosphorylation and GLUT4 translocation." (PMID 22682013, 2012). "Put together, the findings from clinical studies suggest that GBR may reduce glycemia, hypercholesterolemia, fructosamine levels, and HbA1c, and improve insulin and insulin resistance." (PMID 23304216, 2012). "Yet, mTOR may have a negative feedback loop and can inactivate IRS that may lead to poor insulin signaling and insulin resistance in the cardiovascular system." (PMID 22545721, 2012). "Moreover, hepatic insulin resistance mediates the failure of the insulin-signaling pathway, leading to molecular and cellular changes that result in excess accumulation of triglycerides in the hepatocytes." (PMID 22451839, 2012). "Lower insulin resistance might be a compensatory response to decreased insulin level to maintain blood glucose within a normal range." (PMID 23029165, 2012). "Therefore, it is likely that dietary EGCG exerts its antidiabetic activity both through a reduction of insulin resistance and an increase in glucose-induced insulin secretion via protection of functional β cell mass." (PMID 22333133, 2012). "Given this metabolic phenotype of RenTgMK mice, it would be interesting to explore whether the insulin resistance seen in several models of chronic RAS overactivation is insulin-dependent and further studies are warranted." (PMID 23308073, 2012). "The present study is first to our knowledge that evaluates the combined effects of supplementary CrProp and thiamine on insulin resistance and related blood parameters, as well as tissular microelement levels in the insulin-resistant rat model (induced by a high-fructose diet)." (PMID 23065486, 2012). "We found that EEB, rutin, and quercetin may alleviate insulin resistance by improving insulin signaling via p-PKC activity inhibition and glucose uptake enhancement in insulin-resistant cells." (PMID 22548048, 2012). "Although reduction of food intake may initially attenuate insulin resistance, it has been stated that food restriction during the same length of time could lead to a down-regulation of insulin signaling in adipose tissue." (PMID 23056516, 2012). "The Cytoplasmic Polyadenylation Binding Protein (CPEB) interacts with mRNA to control translation; knockout mice that lack CPEB exhibit high-fat-diet-induced liver insulin resistance and do so by having aberrant expression of major insulin signaling molecules, in particular PTEN 3 and Stat3." (PMID 22253608, 2012).
Insulin resistance (continued). "HFD mice had a higher insulin/glucose ratio (1.4-fold; P = 0.020; insulin 91.1±8.8 pmol/l vs 56.8±6.8 pmol/l for controls; glucose 10.9±0.3 mmol/l vs 9.4±0.5 mmol/l for controls) as a marker of insulin resistance." (PMID 22457829, 2012). "For example, metformin may improve insulin resistance and reduce insulin level, counteracting the related mechanisms leading to thyroid proliferation or cancer." (PMID 23300866, 2012). "The increasing demand of insulin in response to a high glycemic diet may exacerbate insulin resistance and lipid dysfunction in subjects with higher BMI, thus leading to a higher risk for developing CHD." (PMID 23284926, 2012). "It is well known that insulin resistance is associated with obesity, but insulin secretion is not affected by body constitution." (PMID 22364391, 2012). "In this regard, in a state of insulin resistance, insulin itself may contribute to accelerated vascular damage as it may display proatherogenic and prohypertensive potentials." (PMID 22973304, 2012). "Chronic elevated circulating insulin level is observed in diabetics and may be due to endogenous (insulin-resistance-related) or exogenous sources (medications)." (PMID 22778714, 2012). "The main goal of the present studies was to determine whether treatment of insulin resistant fatty Zucker rats with CL 316,243 improves both obesity and insulin resistance." (PMID 23056223, 2012). "Being clear that inflammation related to obesity contributes to insulin resistance, the first step in the development of T2D, we set out whether there is a difference in the state of inflammation among insulin resistant subjects and diabetic patients." (PMID 23110196, 2012). "Mean fasting insulin, homeostasis model assessment insulin resistance index (HOMA-IR), triglyceride, total cholesterol, low density lipoprotein cholesterol, free testosterone, total testosterone, carotid intima media thickness (CIMT) levels were significantly higher in PCOS patients." (PMID 23249450, 2012). "Poor in utero nutrition leading to insulin resistance in childhood and thus increased insulin levels may result in increased anabolism in bone, muscle, and adipose tissue and an earlier age at reaching these critical levels of height and/or body fat." (PMID 22448212, 2012). "Despite circulating concentrations of these proteins not being different between the three groups, significant correlations between the levels of these proteins and several functional parameter of T2D and insulin resistance were noted, such as fasting glucose, fasting insulin, HbA1c, and HOMA-IR." (PMID 23304117, 2012). "In addition, Ad-shAcrp30 treatment exhibited clinical signs of glucose and lipid abnormalities and insulin resistance with increased plasma insulin, FFA, TG, TC and LDL-C and decreased HDL-C levels (P<0.01 or P<0.05)." (PMID 23152772, 2012). "As SLE mice also showed mildly elevated plasma insulin concentrations during the entire study, we addressed whether these animals also developed insulin resistance in the liver or visceral adipose tissue." (PMID 23226562, 2012). "Thus, in type 2 diabetes, despite the β-cells working at maximum capacity to produce and secrete insulin, hyperglucagonemia, and hyperglycemia persist due to insulin resistance in the α-cells." (PMID 23316165, 2012). "Long-term linagliptin treatment reduced liver fat content in animals with diet-induced hepatic steatosis and insulin resistance, and may account for improved insulin sensitivity." (PMID 22761701, 2012). "Insulin resistance precedes the development of type 2 diabetes, and is characterized by reduced insulin-dependent glucose uptake into muscle, adipose tissue and other insulin-sensitive peripheral tissues, inadequate suppression of hepatic glucose production, and accumulation of hepatic lipids." (PMID 22389718, 2012).
Insulin resistance (continued). "Insulin resistance is the earliest phenotypic change in these mice, evident by 10–12 days of age, with glucose intolerance to oral glucose challenge and reduced hypoglycemic response to insulin injection by 8–12 weeks of age." (PMID 23028874, 2012). "The development of insulin resistance is thought to occur in response to increased production of pro-inflammatory cytokines by adipose tissue in obesity, that then have an inhibitory effect on insulin signaling pathways in multiple tissues." (PMID 26486919, 2012). "In this setting, insulin resistance may be considered a compensatory mechanism that protects the cells against further insulin stimulated glucose and fatty acid uptake and therefore oxidative damage." (PMID 26557292, 2012). "Besides their potent regulatory role on GH release, its endocrine actions are highlighted by SST/CORT and ghrelin influence on insulin secretion, glucose homeostasis, and insulin resistance." (PMID 23162532, 2012). "Hence, iron excess seems to contribute initially to insulin resistance and subsequently to decreased insulin secretion." (PMID 22752055, 2012). "Adipocyte resistance to the antilipolytic effect of insulin and the consequent elevated plasma free fatty acid levels may play an important role in the development of insulin resistance in muscle and other target tissues." (PMID 22523674, 2012). "Second, insulin resistance (I prefer the expression; reduced insulin sensitivity) may result from hyperinsulinemia." (PMID 22698081, 2012). "While the mechanisms are yet to be investigated, insulin resistance with secondary hyperinsulinemia is the most frequently proposed hypothesis, as insulin may have a possible mitogenic effect via its binding to the insulin-like growth factor-1 receptor." (PMID 22448244, 2012). "ANGPTL4 expression is also stimulated by insulin sensitizing drugs thiazolidinediones via PPARy mediated mechanism suggesting that changes in ANGPTL level could have a role in the development of insulin-resistance." (PMID 22471940, 2012). "In this study, we report our development of a high-throughput procedure to screen for compounds that can prevent palmitic acid-induced myocellular insulin resistance using this enzymatic 2DG uptake assay, and assessment of the anti-insulin-resistant effects of unsaturated fatty acids." (PMID 22409911, 2012). "Indeed, insulin resistance has also been described in type 1 diabetic human under insulin treatment as well as in experimental models without insulin therapy." (PMID 23285277, 2012). "It is also found that ezetimibe could prevent fatty liver by reducing hepatic lipogenesis in mice on a high-fat diet and attenuating diet-induced insulin resistance, a state known to drive hepatic lipogenesis through elevated circulating insulin levels." (PMID 22132342, 2012). "As a result, activation of the mTOR pathway in the cardiovascular system may lead to poor insulin signaling and insulin resistance." (PMID 22545721, 2012). "To identify the involvement of AMPKα2 in the downstream signal pathway of α7-nAChR to enhance insulin sensitivity, we examined if activation of α7-nAChR in AMPKα2−/− mice could improve insulin resistance." (PMID 23251458, 2012). "Subsequent twin studies documented that both defective insulin secretion and insulin resistance were associated with low birthweight in a complex non-genetic and age-dependent manner." (PMID 22643933, 2012). "The percentage of South Asian women with insulin resistance defined by fasting insulin and HOMA-IR values in the upper quartile appeared to show increasing trend across incremental triglyceride-to-HDL cholesterol ratio tertiles but neither result achieved statistical significance." (PMID 23251403, 2012). "Further studies are needed to define the relationship between glucose utilization for fatty acid synthesis and insulin sensitivity, in order to determine if TZDs may be efficacious in preventing insulin resistance in SGA." (PMID 22726273, 2012).
Insulin resistance (continued). "Insulin resistance is closely related with increased accumulation of lipids in peripheral tissues and a reduction in lipid content in these tissues is an effective means to improve insulin sensitivity." (PMID 22860063, 2012). "Also inhibition of PDE3B in adipocytes would counteract with the insulin induced antilipolysis, which would increase fatty acid release resulting in insulin resistance." (PMID 23493150, 2012). "The impaired glucose tolerance may be the result of low insulin production, as shown in other models or of insulin resistance." (PMID 23209676, 2012). "Subsequently, as these β-cells become “exhausted”, the combined effects of insulin resistance and impaired insulin secretion reduce insulin-mediated glucose uptake and utilization by skeletal muscle and prevent insulin-mediated suppression of hepatic glucose output." (PMID 21716678, 2012). "A key role for TNF-α in obesity-related insulin resistance was identified when TNF-α or TNF-α receptors were deleted in both diet-induced obese mice and leptin-deficient ob/ob mice, which resulted in significantly improved insulin sensitivity." (PMID 22110480, 2012). "Nevertheless, the relationship between obesity and insulin resistance is a result of changes in the insulin signal transduction pathway, with a decrease in kinase activity of insulin receptor (IR), insulin receptor substrate 1 and 2 (IRS1, IRS2), and phosphatidylinositol 3-kinase (PI3K), or both." (PMID 23046739, 2012). "Moreover human studies reveal that patients with insulin resistance have lower ghrelin concentrations compared with insulin-sensitive patients." (PMID 23029221, 2012). "Whether this is a consequence of facilitated insulin action following mitigation of insulin resistance remains to be proved (if so, it would actually suggest a cardio-protective role for insulin resistant state – a concept that is alien to current thinking)." (PMID 22952467, 2012). "Insulin resistance in α-cells may result in concurrently unsuppressed glucagon secretion under insulin-stimulatory conditions." (PMID 23316165, 2012). "In addition, low insulin levels and insulin resistance can contribute to a decrease in acetylcholine levels, which represents a possible biochemical link between diabetes mellitus and AD." (PMID 22701480, 2012). "The association between insulin resistance and poor cognitive functioning may involve insulin-degrading enzyme (IDE), which plays a role in both insulin and β-amyloid metabolism." (PMID 22611388, 2012). "Further, the reduced adiponectin levels in septic patients may support insulin resistance in critically ill patients although it was shown, that adiponectin levels and insulin demand were positively correlated during sepsis." (PMID 22272381, 2012). "Therefore, elevated fasting insulin can be considered a surrogate marker of hepatic insulin resistance." (PMID 22947097, 2012). "A considerable percent of women with PCOS display insulin resistance and elevated Insulin level." (PMID 25243003, 2012). "Thus, type 2 diabetes is a two-step process characterized by both insulin resistance and impaired insulin secretion." (PMID 23015803, 2012). "Our inclusion criteria were designed to exclude patients with a metabolic syndrome, but we nevertheless carried out homeostasis model assessment of insulin resistance (HOMA-IR) with the measurement of fasting insulin and glucose concentrations at the time of liver biopsy." (PMID 22479436, 2012). "In vivo, it appears to enhance the insulin signaling pathway and improve insulin resistance." (PMID 23882364, 2012). "As ROS plays important roles in the pathogenesis of insulin resistance, it is likely that longer treatment of db/db mice with reveratrol could improve insulin sensitivity as well." (PMID 23226280, 2012).